DDOST (dolichyl-diphosphooligosaccharide--protein glycosyltransferase non-catalytic subunit)
Description:
Subunit of the oligosaccharyl transferase (OST) complex that catalyzes the initial transfer of a defined glycan (Glc(3)Man(9)GlcNAc(2) in eukaryotes) from the lipid carrier dolichol-pyrophosphate to an asparagine residue within an Asn-X-Ser/Thr consensus motif in nascent polypeptide chains, the first step in protein N-glycosylation. N-glycosylation occurs cotranslationally and the complex associates with the Sec61 complex at the channel-forming translocon complex that mediates protein translocation across the endoplasmic reticulum (ER). All subunits are required for a maximal enzyme activity (By similarity). Required for the assembly of both SST3A- and SS3B-containing OST complexes.
Synonyms: KIAA0115; OST48; OST; WBP1; AGER1; CDG1R; GATD6; OKSWcl45
Tractability: Small molecule: a structure with a bound ligand is known. Antibody: its Gene Ontology location is reachable by antibodies, with high confidence; UniProt predicts a signal peptide or a membrane-spanning region. PROTAC: ubiquitination databases record sites on it; its protein half-life has been measured; a small molecule that binds it is known.
Target class: Enzyme; Transferase
Gene: Protein-coding gene on chromosome 1 (20,651,767 to 20,661,544, reverse strand). Ensembl gene ENSG00000244038.
Subcellular location: Endoplasmic reticulum membrane
Subcellular location (Human Protein Atlas): Endoplasmic reticulum
Pathways (Reactome):
Immune System: Advanced glycosylation endproduct receptor signaling; Neutrophil degranulation; PD-L1(CD274) glycosylation and translocation to plasma membrane
Disease: Maturation of DENV proteins; Maturation of spike protein
Metabolism of proteins: Asparagine N-linked glycosylation; SRP-dependent cotranslational protein targeting to membrane
Cell-Cell communication: Regulation of CDH1 posttranslational processing and trafficking to plasma membrane
Gene Ontology:
Molecular function: enzyme activator activity; protein binding
Biological process: protein N-linked glycosylation; regulation of protein stability; response to cytokine; T cell activation; glycoprotein biosynthetic process
Cellular component: endoplasmic reticulum; intracellular membrane-bounded organelle; membrane; oligosaccharyltransferase complex; oligosaccharyltransferase complex A; oligosaccharyltransferase complex B; azurophil granule membrane; endoplasmic reticulum membrane; plasma membrane
Genetic constraint (gnomAD): Loss-of-function variants: 23 observed, 43.6 expected, observed/expected ratio (o/e) 0.53, 90% interval 0.38 to 0.75. The upper end of that interval is the gene's LOEUF score, 0.75, which puts it in group 3 of 6, group 1 being the genes least tolerant of losing a copy. Missense variants: 485 observed, 526.42 expected, observed/expected ratio (o/e) 0.92, 90% interval 0.85 to 0.99. Synonymous variants: 250 observed, 217.28 expected, observed/expected ratio (o/e) 1.15, 90% interval 1.04 to 1.28.
Gene-disease validity (ClinGen):
ClinGen rates the evidence that DDOST causes each of these diseases.
DDOST-congenital disorder of glycosylation (autosomal recessive): Moderate. DDOST-CDG is a form of congenital disorders of N-linked glycosylation characterized by failure to thrive, developmental delay, hypotonia, strabismus and hepatic dysfunction.
Homologues: Orthologues: chimpanzee DDOST (99% identical), dog DDOST (96% identical), rat Ddost (95% identical), mouse Ddost (95% identical), rabbit DDOST (94% identical), guinea pig DDOST (94% identical), pig DDOST (94% identical), tropical clawed frog ddost (88% identical), zebrafish ddost (83% identical), Drosophila melanogaster Ost48 (60% identical), Caenorhabditis elegans ostb-1 (52% identical).